BUB1B (BUB1 mitotic checkpoint serine/threonine kinase B)
Diseases named in the same sentence as BUB1B in open-access papers (continued):
Sharing a sentence is not in itself a finding about the gene and the disease.
ovarian carcinoma (14 papers, 2009 to 2025). A malignant neoplasm originating from the surface ovarian epithelium. "BUB1 and BUB1B genes were identified as significant hub differentially expressed genes in epithelial ovarian cancer associated with a poor prognosis." (PMID 39048649, 2024). "DO analysis revealed that DEGs PSAT1, FOLR1, ABCB1, SFRP1, SFRP1, BUB1B have a greater association with female reproductive system tumor-related diseases, such as malignant ovarian surface epithelial-mesenchymal tumor, ovarian epithelial carcinoma, and ovarian cancer." (PMID 35719392, 2022). "Reported four genes (BUB1B, BUB1, TTK and CCNB1) that were up-regulated DEGs in ovarian cancer associated with poor prognosis using integrated bioinformatical methods." (PMID 39048649, 2024). "The findings showed that high expression levels of BUB1B, BUB3, or TTK were associated with better survival rates in ovarian cancer patients treated with paclitaxel compared to patients with low expression levels." (PMID 38410481, 2024). "For example, BUB1B, a kinase involved in spindle checkpoint function, has been shown to be a prognostic marker for ovarian epithelial cancer." (PMID 33952272, 2021). "Finally, we identified CCNA2 and BUB1B as candidate hub genes for ovarian cancer progression, as their high expression was correlated with tumor stage and overall survival of ovarian cancer." (PMID 34253236, 2021). "Consequently, BUB1B was hypothesized to facilitate the progression of ovarian cancer by modulating the Wnt/β‐catenin pathway in our study." (PMID 41163302, 2025). "Nevertheless, the function and mechanism of BUB1B in ovarian cancer (OC) remain unknown." (PMID 41163302, 2025). "A Kaplan-Meier survival analysis was carried out to determine the relationship between the expression of BUB1B, TTK, and BUB3 and the overall survival and recurrence-free survival of ovarian cancer patients treated with paclitaxel." (PMID 38410481, 2024). "For instance, four genes (BUB1B, BUB1, TTK, and CCNB1) that are pronouncedly upregulated in ovarian cancer and indicate dismal prognosis were disclosed through bioinformatic methods, and they can be used as potential therapeutic targets for patients with ovarian cancer." (PMID 34434217, 2021). "Furthermore, in the CCLE database, the expression levels of BUB1B, NDC80, ELF3, TFAP2A and hsa-miR-655 were confirmed among different ovarian cancer cell lines." (PMID 33493131, 2021). "BUB1B and NDC80 were validated at a transcription level in multiple cancer types based on the Oncomine database in that BUB1B (Median rank 132, p-value=1.54e-06) and NDC80 (Median rank 192.5, p-value=4.04e-08) were highly expressed in ovary cancer samples compared with normal ovary tissues." (PMID 33493131, 2021). "However, there was no relevant expression of SFRP1 and BUB1B genes detected in the validation set B. Due to the high lethality of ovarian cancer, we took the potential genes obtained from validation set A and validation set B. Thus, altogether, 9 diagnostic genes were obtained." (PMID 35719392, 2022).
colon carcinoma (12 papers, 2006 to 2022). "The BUB1B mutation (Thr40Met) was reported as a germline mutation in a case of colon cancer and in a case of renal clear cell carcinoma but has not been further validated as damaging." (PMID 26102504, 2015). "In addition, mutations in human BUB1B have demonstrated a dominant negative effect by disrupting the mitotic checkpoint when transfected into euploid colon cancer cell lines." (PMID 18425214, 2007). "Conversely, we found that 6 genes involved in the mitotic spindle checkpoint (TTK, BUB1, BUB3, CDC20, MAD2L1, and BUB1B) are overexpressed in colon cancer specimens." (PMID 16919171, 2006). "Furthermore, the expression of BUB1B in colon cancer tissues is higher than in normal colon tissues." (PMID 34787756, 2022).
glioma (11 papers, 2011 to 2023). A benign or malignant brain and spinal cord tumor that arises from glial cells (astrocytes, oligodendrocytes, ependymal cells). "It had been experimentally proven that BUB1B is overexpressed in glioma and associated with tumorigenicity and radio-resistance of glioma." (PMID 36111134, 2022). "It has been reported that RNA levels of a major mitotic spindle assembly checkpoint gene, Bub1b, whose transcript encodes the mitotic checkpoint kinase MAD3L, significantly correlate with glioma grade and survival time." (PMID 25505565, 2013). "Genes associated with the neuronal differentiation pathway (Pcsk9, Runx1, Cebpb, Fzd4, Wnt7a, Ascl1, Fzd2, Edn3, Olig2, and Gpc2), gliomas (Shc1, Cdk4, E2f2, and Ccnd1), and cell cycle (Bub1b, Bub, Ccnb1, Ccnb2, and Cdc20) were significantly downregulated." (PMID 36147849, 2022). "Treatment with MNF also sensitized C6 glioma tumor xenograft to growth arrest via the downregulation of Galnt3 and other cell cycle regulators, such as Ccna2, Cdkn3, and Bub1b." (PMID 25505565, 2013). "Preliminary immunohistochemistry evidence indicates that the proteins encoded by the SAC genes investigated here are also induced in gliomas, with BUB1B again being the most significant." (PMID 22022424, 2011). "In pairwise comparisons of glioma samples, two genes (BUB1B, CDC20) showed significant difference between grade II and grade IV (p<0.05), while expression in grade III does not significantly differ from grade II or grade IV for most genes." (PMID 22022424, 2011). "Thus, the expression level of BUB1B reveals information on the survival probability for glioma patients beyond that revealed by grade alone." (PMID 22022424, 2011). "Measuring the expression of BUB1B gene might be a useful addition to the repertoire of clinicians for staging gliomas." (PMID 22022424, 2011). "This highlights the possibly useful role of CDC20 and BUB1B in estimating grades of glioma samples." (PMID 22022424, 2011). "Thus, qPCR assays of SAC genes, particularly BUB1B, might be used as an objective complement to histological diagnosis for identification of glioma grades, MIB Li, MI, and the multigene RNA profiles that have been proposed." (PMID 22022424, 2011). "RNA levels of eight major mitotic spindle assembly checkpoint (SAC) genes (BUB1, BUB1B, BUB3, CENPE, MAD1L1, MAD2L1, CDC20, TTK) significantly correlated with glioma grade and six also significantly correlated with survival time." (PMID 22022424, 2011). "Expression of six SAC genes, BUB1, BUB1B, CDC20, CENPE, MAD1L1 and TTK were found to be significantly positively correlated with WHO grades of glioma patients (p<0.01)." (PMID 22022424, 2011). "Nevertheless, antibody stains for proteinsBUB1, BUB1B, BUB3, CDC20, and TTK were at significantly higher levels in high grade glioma than in normal brain by this test." (PMID 22022424, 2011). "Interestingly, Ki-67 RNA level was outperformed by BUB1B and CDC20, overall, and by BUB1 and TTK when applied to grade II gliomas." (PMID 22022424, 2011). "A single marker such as BUB1B will not capture all the variability in subtypes of glioma." (PMID 22022424, 2011).
liver cancer (10 papers, 2018 to 2024). An epithelial or non-epithelial malignant neoplasm that arises from the liver. "We also found that the hub upregulated genes in this network—MCM3, BUB1B, DLGAP5, DIP5, ECT2—have been linked to liver cancer according to wide literature reports." (PMID 39628446, 2024). "Qiu reported that BUB1B may promote the proliferation of liver cancer cells by raising the mTORC1 signaling pathway." (PMID 36979826, 2023). "Finally, survival analysis, based on clinical information from the TCGA-liver cancer datasets, revealed that the high expression of EZH2, GINS1, and TPX2 correlated positively with higher risk, CENPF and BUB1B were quite the contrary." (PMID 30100882, 2018). "Our results indicate that BUB1B was significantly decreased in liver fibrosis and increased in AFB1 and liver cancer samples, for the reason that fibrosis is reversible liver damage and the body tries to protect itself from being damaged." (PMID 36829489, 2023). "In addition to CCNB1, CDK1, CDC45, BUB1B, and CCNA2, we also identified five hub genes in Chinese liver cancer, namely AURKA, KIF11, TOP2A, TPX2, and HMMR, which play a crucial role in regulating the cell cycle." (PMID 34257537, 2021).
pancreatic cancer (10 papers, 2018 to 2024). "In this study, we showed that mitotic spindle assembly checkpoint regulators TTK and BUB1B were highly expressed in human pancreatic cancer tissues and worked as prognostic factors in PDAC, which are in consistent with previous reports." (PMID 38711083, 2024). "P/LP variants of APC, BRCA2, BUB1B and ENG were identified in patients with pancreatic cancer, and MSH6 was identified in an NPaMC patient with both colorectal and esophageal cancers." (PMID 36896836, 2023). "APC, BRCA2, BUB1B, ENG and MSH6 were associated with cancer predisposition, and pathogenic/likely pathogenic (P/LP) variants occurred in 6% [pancreatic cancer (4/72); all-cancer (5/90)] and 54% (49/90) carried only variants of uncertain significance (VUS) among cancer patients." (PMID 36896836, 2023). "Eight genes (BUB1, BUB1B, CCNA2, CCNB2, CDC6, CDC20, CDK1, and TTK) among 21 common network genes were correlated with worse survival of pancreatic cancer, highlighted with P-value significantly <0.05." (PMID 32117719, 2020). "Our study delves into the intricacies of nab-paclitaxel resistance in a model of pancreatic adenocarcinoma, PANC-1, and pinpoints the pivotal role played by three SAC proteins—BUB1B, TTK, and BUB3—in determining sensitivity of a pancreatic cancer cell line to paclitaxel." (PMID 38410481, 2024).
pancreatic ductal adenocarcinoma (10 papers, 2019 to 2025). An infiltrating adenocarcinoma that arises from the epithelial cells of the pancreas. "Overexpression of BUB1 and BUB1B in tumor tissues is related to a poor prognosis in pancreatic ductal adenocarcinoma, and it is also associated with advanced tumor stage and tumor development." (PMID 35493295, 2022). "BUB1B is the hub gene of pancreatic ductal adenocarcinoma (PDAC), and the expression of BUBR1 encoded by BUB1B can predict poor prognosis in pancreatobiliary-type tumors." (PMID 36741321, 2023). "Recent research showed that the up-regulation of BUB1B was associated with worse OS and DFS in pancreatic ductal adenocarcinoma and correlated with advanced tumor stage and tumor development." (PMID 33431813, 2021). "Similarly, in pancreatic ductal adenocarcinoma, H3K18la enrichment regulates mitotic checkpoint regulators TTK and BUB1B transcription to tumorigenesis." (PMID 41310104, 2025).
microcephaly (9 papers, 2015 to 2023). A congenital or acquired developmental disorder in which the circumference of the head is smaller than normal for the person's age and sex. "Shortened mitosis, compromised genomic integrity, and massive cell death are considered the major causes of microcephaly in subjects with BUB1B mutations." (PMID 35804254, 2022). "Studies of mosaic variegated aneuploidy (MVA) patients harboring mutations in Bub1b and Cep57 also showed aneuploidy and microcephaly." (PMID 26044958, 2015). "BUB1B mutation in humans and its deletion in mice cause microcephaly." (PMID 37900274, 2023). "However, as mutations of BUB1B gene may cause microcephaly and other malformations in MVA1 subjects is a matter of debate." (PMID 35804254, 2022). "Monoallelic or biallelic mutations in the Budding Uninhibited by Benzimidazole 1B (BUB1B) gene, which encodes the BUB-related 1 (BUBR1) protein, have been found in several MVA families presenting microcephaly." (PMID 31878213, 2019). "Our observation of disrupted neural progenitor proliferation in BUBR1 [BUB1B]- and TMEM216-deficient brains is consistent with the clinical symptoms, such as microcephaly, found in human patients." (PMID 26206566, 2015). "Therefore, subjects who do not carry genetic mutations in BUB1B have milder phenotype with absence of microcephaly compared to those with BubR1 deficiency who show severe phenotype including microcephaly." (PMID 35804254, 2022).
multiple myeloma (7 papers, 2017 to 2025). "This increased Bub1β expression promotes myeloma cell proliferation and is associated with a poor survival rate." (PMID 29163849, 2017). "Elevated levels of BUB1B facilitate the proliferation of multiple myeloma cells through the CDC20/CCNB signaling axis." (PMID 40076684, 2025). "For example, circBUB1B_544aa and the host gene BUB1B act synergistically to exacerbate multiple myeloma, circFOXO3 negatively regulates the host gene FOXO3 in osteoarthritis through activation of autophagy." (PMID 38150467, 2023). "Previous studies indicate that expression levels of BUB1B, which is a spindle-assembly checkpoint gene, were highly upregulated in multiple myeloma patients and that these levels were strongly correlated with unfavorable outcomes." (PMID 36199789, 2022). "BUB1B evokes chromosomal instability via phosphorylation of CEP170 to promote myeloma malignancy." (PMID 41163302, 2025). "Moreover, BUB1B may contribute to drug resistance to bortezomib and adriamycin in multiple myeloma." (PMID 40076684, 2025). "The expression of Bub1β, a kinase involved in the SAC pathway, is significantly increased in patients with aggressive myeloma." (PMID 29163849, 2017).
sarcopenia (7 papers, 2012 to 2024). Progressive decline in muscle mass due to aging which results in decreased functional capacity of muscles. "Bub1b, also known as BUBR1, encodes a mitotic regulatory factor, and mice carrying monoallelic BubR1 mutations are prone to sarcopenia correlating with mTORC1 hyperactivity." (PMID 38331723, 2024). "Accelerated sarcopenia and a shortened lifespan were observed in mice with low levels of the spindle assembly checkpoint protein BubR1, including Bub1bH/H mice with two hypomorphic alleles and Bub1b+/GTTA mice with the human nonsense mutation 2211insGTTA." (PMID 33328881, 2020).
brain tumor (6 papers, 2015 to 2023). "The knockdown of BUB1B/BUBR1 inhibited the expansion of brain tumor–initiating cell isolates, both in vitro and in vivo, without affecting the proliferation of the human neural stem cells or astrocytes." (PMID 37644431, 2023). "Consistent with this, the knockdown of BUB1B inhibited brain tumor-initiating cells -driven tumor formation." (PMID 36577966, 2022).
childhood cancer (6 papers, 2007 to 2022). "This is seen in families with missense mutations of BUB1B, which results in Mosaic Variegated Aneuploidy (MVA), a syndrome characterized by aneuploidy, growth retardation and childhood cancer." (PMID 20411023, 2010).
endometrial carcinoma (6 papers, 2022 to 2025). A malignant tumor arising from the epithelium that lines the cavity of the uterine body. "In endometrial cancer, BUB1B expression was found to be relevant to the infiltration of activated CD4 + T cells and CD8 + T cells." (PMID 41163302, 2025). "This study aimed to evaluate the expression and clinical significance of budding uninhibited by benzimidazole 1 (BUB1) and BUB1 mitotic checkpoint serine/threonine kinase B (BUB1B) in endometrial carcinoma (EC)." (PMID 39048649, 2024). "The focus of the immunohistochemical experiments was to investigate expression of BUB1 and BUB1B in endometrial cancer and normal endometrial tissue, and thus only 20 cases were selected." (PMID 39048649, 2024). "The expression of microRNA (miR)-524-5p reduced the migration and invasion of Ishikawa endometrial carcinoma (EC) cells, while decreasing BUB1, BUB1B, CCNA2, and CDCA8 expression." (PMID 37853361, 2023).
melanoma (6 papers, 2014 to 2024). A malignant, usually aggressive tumor composed of atypical, neoplastic melanocytes. "BUB1B gene alterations were more frequent in EC and melanoma (frequency > 5%) and the alterations were predominantly mutations." (PMID 39048649, 2024). "Other genes that are lost on CFA30 include two mitotic regulators involved in chromosome segregation, namely Knstrn and Bub1b, with significantly lower Bub1b transcripts detected in melanoma tumours compared with matched normal tissue." (PMID 34822659, 2021). "Downregulation of BUB1B, CDK1 and DEK provides a mechanistic explanation for the aberrant spindles and defects in cytokinesis observed after sustained depletion of CPEB4 in melanoma cells." (PMID 27857118, 2016). "Furthermore, additional RNA-immunoprecipitations demonstrated binding of CPEB4 to the 3′-UTR of BUB1B, CDK1 and DEK mRNAs in melanoma cells." (PMID 27857118, 2016).
sarcoma (6 papers, 2021 to 2024). A usually aggressive malignant neoplasm of the soft tissue or bone. "Higher expression levels of BUB1, BUB1B, and BUB3 were found in sarcoma samples and were associated with lower overall and disease-free survival in sarcoma patients." (PMID 38473259, 2024). "In the present study, analysis using the Oncomine and GEPIA datasets revealed that the expression of BUB1 and BUB1B were higher in human sarcomas than in normal tissues." (PMID 33872216, 2021). "Survival analysis revealed that the higher expression levels of BUB1, BUB1B and BUB3 were associated with lower overall and disease-free survival in patients with sarcomas." (PMID 33872216, 2021). "Notably, the expressions of BUB1 and BUB1B are significantly higher in sarcomas compared to normal tissues." (PMID 33872216, 2021). "This study implies that BUB1, BUB1B and BUB3 are potential treatment targets for patients with sarcomas and are new biomarkers for the prognosis of sarcomas." (PMID 33872216, 2021). "CDK1, KIF11, AURKB, MAD2L1, BUB1B and CCNB2 were highly expressed in sarcoma and were markedly related to worse OS." (PMID 34838000, 2021). "Three BUB family members have been identified in patients with different types of sarcoma: BUB1, BUB1B and BUB3." (PMID 33872216, 2021). "We found that the expression levels of BUB1, BUB1B and BUB3 were higher in sarcoma samples and cell lines than in normal controls." (PMID 33872216, 2021). "BUB1, BUB1B, and BUB3 may serve as a future potential treatment targets and prognostic biomarkers for patients with sarcomas." (PMID 38473259, 2024). "Additionally, in comparison to the normal controls, the sarcoma tissues and cells exhibited obviously high BUB1, BUB1B, and BUB3 expression." (PMID 36439516, 2022). "In addition, using the Kaplan-Meier Plotter and GEPIA databases, we determined that the overall and disease-free survival of sarcoma patients were significantly lower in patients with overexpressed BUB1 and BUB1B." (PMID 33872216, 2021). "Our results indicated that BUB1, BUB1B and BUB3 may serve as oncogenes in sarcomas and have significant prognostic values." (PMID 33872216, 2021).
colon adenocarcinoma (5 papers, 2018 to 2021). "Interestingly, it was reported that low expression of BUB1B resulted in the initiation and progression of human colon adenocarcinomas." (PMID 32977361, 2020).
adrenocortical tumors (4 papers, 2011 to 2021). "The combination of BUB1B, DLGAP5, and PINK1 can serve as a predictor of a poor outcome in adrenocortical tumors." (PMID 35095717, 2021). "Combined expression of BUB1B and PINK1 was the best predictor of overall survival in adrenocortical tumors by microarray." (PMID 22022424, 2011). "More recently, analysis of the combined expression of TCF21 and BUB1B in adult and pediatric adrenocortical tumors showed a negative correlation between the expression levels of TCF21 and BUB1B in adult ACCs." (PMID 33729392, 2021).